RIPK3 (receptor interacting serine/threonine kinase 3)
Diseases named in the same sentence as RIPK3 in open-access papers (continued):
Sharing a sentence is not in itself a finding about the gene and the disease.
cancer (continued). "After more than 30 years of exploration of the mechanism of programmed death of cancer cells, necrotic apoptosis has been confirmed to be a typical form of cancer cell necrosis, which is mediated by receptor interacting protein kinase 3 (RIPK3) and mixed-lineage kinase domain-like synergism." (PMID 35501667, 2022). "In addition, RIPK3 expression is silenced in most cancer cells due to genomic methylation." (PMID 39872161, 2022). "However, the exact mechanism by which RIPK3 negatively regulates cancer development and progression remains unclear." (PMID 36161785, 2022). "Therefore, we propose that NMR-specific loss-of-function mutations in the necroptosis regulators RIPK3 and MLKL may be one of the mechanisms underlying the attenuated tissue inflammatory response and remarkable cancer resistance of NMRs." (PMID 35354912, 2022). "Because RIPK3 expression is differentially expressed in CCA cell lines and it has been previously demonstrated that RIPK3 expression predicts necroptosis response in several cancers, we hypothesized that the expression of RIPK3 determines necroptosis responsiveness in CCA cells." (PMID 31914150, 2020). "Moreover, RIPK3 expression is lost in many cancer cell lines and in primary human cancers." (PMID 33179413, 2020). "Thus, this shows a protective role for RIPK3 against tumor progression that could potentially be used for cancer therapy." (PMID 31766571, 2019). "Furthermore, reports indicate that genomic methylation and/or hypoxia may play a pivotal role in silencing RIPK3 expression in many cancer cell lines." (PMID 31122251, 2019). "A 4-day treatment of A375 and SkMel28 cancer cell lines, which have no initial RIPK3 expression (but also no genetic mutations of RIPK3), with low concentrations of AXL/TYRO3 inhibitor BMS-777607 resulted in a regain of RIPK3 expression at both mRNA and protein levels." (PMID 30157175, 2018). "While RIPK3 expression has been shown to be lost in several cancer cell lines and cancer types, no systematic evidence for the extent of this loss across cancer types or the mechanisms driving this loss have been reported." (PMID 30157175, 2018). "Furthermore, we speculate that other dsRNA mimics or oncolytic RNA viruses that employ molecular mechanisms similar to that of PolyIC might also lead to enhanced immune activation in RIPK3-expressing cancers." (PMID 25888634, 2015). "A limitation of our study is that the functional impact of GADD45β-RIPK3 interaction has been primarily assessed in cell lines; Future studies should explore whether GADD45β exerts similar regulatory functions in primary immune cells or in vivo models of necroptosis-driven inflammation and cancer." (PMID 41354733, 2025). "Necroptosis, a regulated form of necrotic cell death mediated by receptor-interacting protein kinases RIPK1 and RIPK3, and the pseudokinase MLKL, has emerged as a potential alternative pathway to induce cancer cell death." (PMID 41303584, 2025). "Given that cancer is often characterized by an imbalance between apoptosis and necroptosis, we investigated the role of the SPOP/RIPK1/RIPK3 axis in tumors." (PMID 41122967, 2025). "In the context of cancer, SPOP/RIPK1/RIPK3 axis is dysregulated across multiple cancer types, and the combination of the Smac mimetic SM164 enhances the antitumor efficacy of sunitinib in tumors with high expression of SPOP/RIPK1." (PMID 41122967, 2025). "Ultimately, we delve into strategies for targeting PANoptosis in cancer therapy, including targeting various molecules in the PANoptosis pathway, such as ZBP1, RIPK1, RIPK3, Caspases and other novel strategies like nanoinducers and viral vectors." (PMID 40364845, 2025). "Key necroptotic regulators like RIPK1, RIPK3, and MLKL are often altered in cancer, allowing cells to evade necroptosis." (PMID 40893939, 2025).
cancer (continued). "In BMDCs, we found upregulation of the costimulatory molecule CD86 upon interaction with necroptotic MOC1 cells which was dependent on active RIPK3 and MLKL in carcinoma cells and was blocked by necrostatin-1." (PMID 40345706, 2025). "Nanomedicines can initiate a cascade leading to the rupture of cancer cell membranes and subsequent cell death by targeting specific receptors or signaling proteins involved in necroptosis, such as RIPK1 or RIPK3." (PMID 39209834, 2024). "Regarding the regulation of cancer cell necroptosis by SPOP, this study suggests that PIM2 and ERK2 kinase can fine-tune key molecules through phosphorylating T403, T412, and S413 of RIPK3." (PMID 39540935, 2024). "Thus, modulating RIPK1/RIPK3 signaling may be advantageous for overcoming cancer." (PMID 39540935, 2024). "Next, we evaluated the relationship between the copy number variations of RIPK3 and MLKL, the key genes of necroptosis in pan-cancer, and the levels of immune infiltration of different immune cells using the TIMER database." (PMID 37000317, 2023). "The role of RIPK3-MLKL in necroptosis has been widely investigated in a broad physiological and pathological context, including different types of cancer." (PMID 36650126, 2023). "In cancer cell lines that ubiquitously express RIPK1, the availability of RIPK3 correlates with their sensitivity to necroptosis induction." (PMID 36774342, 2023). "In pancreatic cancer, RIPK1, RIPK3, FADD, and MLKL were all increased, accompanied by accelerated cancer cell growth." (PMID 35814424, 2022). "Some cancer cells escape from necroptosis by decreasing the expression of key necroptosis mediators, including CYLD, RIPK3, and MLKL." (PMID 35864548, 2022). "Previous studies have shown that RIPK3, RIPK1, and MLKL are the most important factors involved in necroptotic, playing important roles during cancer progression." (PMID 36110223, 2022). "Relative expressions of RIPK1, RIPK3, and MLKL proteins were significantly (0.001) elevated in both HepG2 and A549 cancer cells after treatment with the IC50 of the CM derivative, when compared to the untreated cells." (PMID 36432094, 2022). "Downregulation of expression of several key necroptosis mediators in cancer has been reported, such as CYLD, MLKL, and RIPK3." (PMID 36065304, 2022). "Necroptosis is a programmed cell death mode mediated by three major mediators, RIPK1, RIPK3, and MLKL, and has been shown to play a role in various cancers." (PMID 35965497, 2022). "For instance, the knockout of the necroptosis key molecules such as RIPK1, RIPK3, or MLKL in cancer cells markedly reduced tumorigenicity." (PMID 36505813, 2022). "Of these DEGs, 6 (EGFR, GATA3, DIABLO, CFLAR, RIPK3, and MAPK8) were repressed, while (ZBP1, PLK1, SPATA2, BCL2, ALK, FASLG, TNFRSF21, and LEF1) were upregulated in cancer cases." (PMID 35610275, 2022). "Although previous studies have shown that RIPK3 is not involved in the activation of B cells, T cells or macrophages, recently it has been reported that RIPK3 regulates the activation of NKT cells activating the immune response and the lysis of cancer cells." (PMID 33567618, 2021). "Dysregulation of RIPK3 and MLKL levels, and inactivation of this inflammatory cell-death pathway, is commonly seen in numerous cancers (e.g.7–9)." (PMID 32393742, 2020). "While RIPK1, which acts in concert with RIPK3 to form fibrils and phosphorylate MLKL, is consistently preserved in cancers because it is also required for the operation of the TNF/TNFR1/NF-κB signaling axis." (PMID 32393742, 2020). "Last but not least, aurora kinase inhibitor CCT137690 can indirectly activate RIPK1, RIPK3, and MLKL in PDAC in vivo, which leads to the initiation of necroptosis and the inhibition of cancer growth and metastasis." (PMID 33665167, 2020). "RIPK3 and MLKL expression seems to vary among tissue samples from different subtypes and stages of cancer, and downregulation of necroptosis mediators has also been published in various cancers." (PMID 31719524, 2019).
cancer (continued). "Thus, induction of RIPK3 expression in cancer could prove to be a double-edged sword." (PMID 30157175, 2018). "A growing list of compounds and anticancer drugs with various primary mechanisms of action, have been reported to initiate programmed necrosis or necroptosis in different cancer cells via mediated RIPK1, RIPK3, MLKL, and HMGB1." (PMID 27429198, 2016). "We demonstrate that genetic knockout of necroptotic genes RIPK1, RIPK3, or MLKL in cancer cells significantly attenuated their abilities to grow in an anchorage-independent manner." (PMID 26959742, 2016). "Upon co-culture with fluorescently labeled MOC1 cells undergoing TSZ-induced necroptosis, BMDMs showed increased uptake of carcinoma cell debris, which was completely absent with RIPK3–/– or MLKL–/– carcinoma cells." (PMID 40345706, 2025). "Higher levels of RIPK3 were detected in both Karpas-299 and CT26 cells after treatment with decitabine, demonstrating that decitabine treatment can lead to re-expression of this key biomarker, which is often silenced in cancer cell lines." (PMID 38727208, 2024). "In addition, by activating downstream RIPK3-driven cell death, TRZ2 proficiently restrains normal mitochondrial function and activity, leading to cancer cell necroptosis." (PMID 38806468, 2024). "Additionally, under the effects of SMAC mimics (including SM164) and pan-caspase inhibitors (including Z-VAD-FMK), RIPK3 can interact with RIPK1 to form necrosomes, leading to the phosphorylation of MLKL and necroptosis of cancer cells." (PMID 38684668, 2024). "For example, RIPK3 was not expressed in two-thirds of over 60 cancer cell lines examined in a previous study, suggesting that tumours acquire resistance to necroptosis to survive." (PMID 38213773, 2024). "Therefore, activation of RIPK3, on the one hand can induce TRIM28 in cancer cells to repress and stimulate the increase of immunostimulatory cytokines to enhance the TME." (PMID 38553639, 2024). "The expression of RIPK3 was positively correlated with the level of immune cell infiltration in cancers like ACC and GBM, but in BUC, it was not strongly correlated with the level of immune cell infiltration." (PMID 37000317, 2023). "Therefore, inducing necroptosis by activating key regulators of necroptosis, including RIPK1, RIPK3 and MLKL, has emerged as a promising option for therapy for different cancers, including EC." (PMID 37564206, 2023). "Cumulative evidence supports that RIPK3 protein and transcripts are not detectable in some types of primary tumors and cancer cell lines, which has been attributed to the hyper-methylation of the promoter region of RIPK312,28–30." (PMID 36650126, 2023). "Several studies have shown that RIPK3 protein expression is absent or reduced in two-thirds of 60+ cancer cell lines tested." (PMID 36361505, 2022). "Furthermore, RIPK3 promoted TNF-induced ROS by activating multiple enzymes and the ROS bursts inhibited metastasis by killing cancer cells." (PMID 35814424, 2022). "On the one hand, the downregulation of the expression of numerous key molecules in necroptosis such as RIPK1, RIPK3, and MLKL has been found in different types of cancer cells, suggesting that cancer cells may evade necroptosis to survive." (PMID 36505813, 2022). "In contrast, in cancer cell types with a RIPK3-negative background, the function of GPx1 switched to promoting an antiapoptotic effect." (PMID 34158609, 2021). "In addition to RIPK1, the necroptotic mediators RIPK3 and MLKL are also involved in cancer and have influence on prognosis." (PMID 33567618, 2021). "The absence of GPx1 augmented TNF-α-induced apoptosis in various RIPK3-negative cancer cells by markedly elevating the level of cytosolic H2O2, which is derived from mitochondria." (PMID 34158609, 2021). "In RIPK3-negative cancer cells, the apoptosis program is inhibited by elevated NF-κB-dependent survival gene expression." (PMID 34158609, 2021).
cancer (continued). "It is important to note that RIPK3 is not expressed in most cancer cell lines due to methylation-dependent regulations, however HaCat cells were described to be sensitive to TzB-induced necroptosis." (PMID 33937329, 2021). "Overall, our studies demonstrate that the anti-apoptotic function of GPx1 is dependent on the absence of RIPK3 expression in cancer cells." (PMID 34158609, 2021). "Lack of RIPK3 expression has also been reported in many other cell types, including hepatocyte and cancer cells." (PMID 32332696, 2020). "Moreover, downregulation of necroptosis mediators such as RIPK3 and MLKL in tumors suggests an escape mechanism from necroptosis in cancer." (PMID 33194736, 2020). "Here, we report for the first time that the key necroptotic proteins RIPK1, RIPK3 and MLKL, which have been reported to be lost or harbor reduced expression in other cancers, were expressed in both CCA primary tissues (TCGA database) and a panel of CCA cell lines." (PMID 31914150, 2020). "The fact that FADD, a target of HPV, is a negative regulator of RIPK3-mediated necrosis may explain the strong necroptotic response in HPV-positive cancer cells that express RIPK3." (PMID 25888634, 2015). "These PANoptosome components, but not RIPK3, showed an abnormally high expression in cancers." (PMID 38436818, 2025). "RIPK3 expression is absent or reduced in many cancer cell lines." (PMID 40301325, 2025). "The development of cancer has been the subject of extensive research, with a total of 615 papers examining the effects of RIPK1, 119 papers investigating the effects of RIPK2, 550 papers exploring the effects of RIPK3, and 54 papers analyzing the effects of RIPK4." (PMID 38164277, 2024). "Therefore, in analogous RIPK3-negative cancers, demethylating agents such as decitabine, RG108, and 5-azacytidine, which reduce DNA methylation near the transcription initiation site, can be used to restore the expression of RIPK3." (PMID 38684668, 2024). "Additionally, necroptosis may fuel carcinogenesis by inducing adaptable immunosuppression, as indicated by the upregulation of RIPK1, RIPK3, and MLKL in some aggressive cancers, including lung cancer and glioblastoma." (PMID 37612409, 2023). "Among them, the synergy with ferroptosis, further RIPK1/RIPK3/MLKL studies, the mechanism and translational applications with inflammation and oxidative stress, and the therapeutic potential to treat cancer and neurodegenerative diseases might be the rising and promising research areas." (PMID 35769473, 2022). "Moreover, testing of more than 60 cancer cell lines showed absence of RIPK3 protein expression in two-thirds of these cancer cell lines, which was restored upon treatment with the hypomethylating agent decitabine." (PMID 36389725, 2022). "In general, we believe that RIPK3 may have a negative regulatory effect on tumorigenesis, different from RIPK1, and it has been reported in the reference that RIPK1 is involved in the NF-κB signaling pathway to regulate cancer development." (PMID 33440739, 2021). "RIPK3 activation inhibits the chromatin binding activity of TRIM28 leading to the transcriptional activation of cytokines, which then promotes immunoregulatory processes, such as dendritic cell maturation and further cytokine production, which then contribute to anti-cancer responses." (PMID 34419074, 2021). "Additionally, RIPK3 is downregulated in breast, colorectal, melanoma, and AML cancers." (PMID 33567618, 2021). "Inhibitors of heat shock protein 90 (HSP90), a molecular chaperone controlling the RIPK3 and MLKL stability and function, such as kongensin A, 17AAG, IPI-504 and Alvespimycin (17-D MAG), both in clinical trials in cancer patients, may indirectly impair necroptosis." (PMID 33050394, 2020). "Combining LUBAC inhibition with cell death-inducing treatments might be a potentially effective approach to induce immunogenic cell death of cancer cells lacking Ripk3 and/or Caspase-8 activity." (PMID 29867129, 2018).
cancer (continued). "Therefore, loss of RIPK3 and MLKL expression as observed in many cancer cells would likely not compromise the MLKL-mRNA approach described here." (PMID 30143632, 2018). "Although in vitro data suggests that cancer cells lacking expression of RIPK3 are invasive, the physiological role of RIPK3 in a disease-relevant setting remains unknown." (PMID 27344176, 2016). "Caspase inhibitor and/or second mitochondria-derived activator of caspase mimetic, which sensitize cells to RIPK1- and RIPK3-dependent necroptosis downstream of tumor necrosis factor receptor-like death receptors, also did not alter the response of cancer cells to chemotherapeutic agents." (PMID 25675296, 2015). "In this case, it would then follow that too much mitochondrial metabolism might inhibit the Warburg effect whereby cancer cells rely on glycolysis to produce anabolic intermediates, which would not be advantageous to a cancer cell and, therefore, RIPK3 would be selected against." (PMID 40010643, 2025). "However, RIPK3 is not universally expressed in many cancer cells; thus, MLKL, a final executioner of necroptosis signaling pathway, could be a potential target in these type of cancer cells." (PMID 36361505, 2022). "In conclusion, we provide the first systematic evidence that most human cancer cell lines escape from necroptosis, independent of their tissue of origin or cancer type, and identify the first two oncogenic alterations upstream of the RIPK3 expression suppression." (PMID 30157175, 2018). "Whether or not cancer necroptosis was essential for the release of IL-1α is difficult to judge, because both cell death and IL-1α release were dependent on regulation by RIPK3." (PMID 25888634, 2015). "The inhibition of necroptosis through downregulation of its main driver (RIPK1, RIPK3, and MLKL) has been observed in different cancer types, showing in some cases also a negative impact on patient survival." (PMID 34745951, 2021). "It is not surprising that RIPK1, RIPK3, and MLKL in cancer play a central role in modulating necroptosis." (PMID 33567618, 2021). "Unlike RIPK3 and MLKL, RIPK1 expression is positively correlated with cancer development." (PMID 39872161, 2022). "These screen results were validated by testing 23 randomly selected cancer cell lines, which showed a complete resistance to TSZ- and TNFα+Cycloheximide+zVAD.fmk (TCZ)-induced necroptosis, lack of RIPK3 expression, and lack of MLKL Ser358 phosphorylation upon stimulation with TSZ treatment." (PMID 30157175, 2018). "Importantly, transcriptomics analysis of the screened 941 cancer cell lines revealed that high AXL and TYRO3 mRNA levels predict both resistance to necroptosis and low RIPK3 mRNA levels, but not those of RIPK1, MLKL, or any other pro-necroptotic genes." (PMID 30157175, 2018).